EGFR (epidermal growth factor receptor)
Diseases named in the same sentence as EGFR in open-access papers (continued):
Sharing a sentence is not in itself a finding about the gene and the disease.
tumor (continued). "Notably, MEK and EGFR inhibitors cooperate to block EGFR inhibitor-resistant CRC tumor growth, and we propose therefore that CCT3833 is effective in CRC because it targets the two key pathways downstream from mutant RAS and the hyperactivated receptor tyrosine kinases such as EGFR." (PMID 33130216, 2021). "Given that EGFR-mediated signalling has been established to upregulate PD-L1 expression on tumour cells, it had originally been hypothesized that the treatment landscape for such cancers could be revolutionized by CD8 T-cell enhancing immunotherapies like PD-L1 inhibitors." (PMID 35052732, 2021). "Moreover, the γ2 chain binding to EGFR may also represent a critical event during tumor progression." (PMID 33920762, 2021). "Perfusion-weighted and/or diffusion-weighted MRI features have been used to predict EGFR amplification and MGMT-methylation, whereas MR spectroscopy and amino acid tracer PET imaging (FET–PET) can predict IDH1 mutation status due to its effects on tumor metabolism." (PMID 33578746, 2021). "Although none of these patients experienced an objective response, one with carcinoma of unknown primary and EGFR amplification (copy number 8.45) and treated with panitumumab showed tumor shrinkage in some of the metastatic lesions; however, treatment benefit for the remaining patients was limited." (PMID 34900683, 2021). "In addition, anti-EGFR-based chemotherapy showed a higher early tumor shrinkage (ETS) rate (68.2% vs. 49.1% in FIRE-3; 64% vs. 45% in PEAK) and deeper DpR (48.9% vs. 32.3%, p<0.0001 in FIRE-3; 65% vs. 46%, p=0.0007 in PEAK) compared with anti-VEGF-based chemotherapy." (PMID 34868987, 2021). "Maybe, high PD-L1 expression in EGFR-mutant patients may be only a result of the oncogene drive, rather than the main cause of tumor immune escape." (PMID 34484468, 2021). "Among patients receiving osimertinib in second-line with a T790M resistance mutation after failure of an earlier generation EGFR TKI, the maximum EGFR somatic allele frequency of EGFR variants measured in circulating tumor DNA does not appear to predict response rate or survival." (PMID 33869038, 2021). "Based on the characterization of tumor tissue, the five EGFR mutations could be detected by the cobas® EGFR Test while two patients harbored an EGFR Ex19Del included in the cobas® EGFR Test but not included in the ddPCRTM EGFR exon 19 deletion screening kit." (PMID 34441254, 2021). "In another case report, a divergent EGFR gene profile was found in a patient who presented with multiple synchronous tumour lesions in separate lungs, although only a limited gene panel was used in this study, and certain actionable genes might have been missed with this approach." (PMID 34299215, 2021). "Therefore, VEGF and EGFR inhibitors have a significant role in various tumor types." (PMID 33562829, 2021). "Importantly, Apt@GO@Au-His@a-ZnO@DOX NCs exhibited much higher targeting efficacy and tumor inhibition to EGFR-positive A549 cells than that of GO@Au-His@a-ZnO@DOX NCs according to the laser scanning confocal microscope (LSCM) images for cellular uptake and in vivo experiments." (PMID 34322025, 2021). "Considering the recurrent involvement of the EGFR pathway through different hit genes in different cell lines, it is likely that synthetic lethality with pevonedistat arises by targeting this pathway in a tumor-specific way, depending on the molecular alterations leading to its oncogenic activation." (PMID 34359705, 2021). "However, the upstream regulation of ILT4 overexpression and its function in tumor immunity of NSCLC with EGFR activation remains unclear." (PMID 33537094, 2021). "Poor-quality tumour DNA precluded assessment of ERBB3 mutation(s) in our family, noting that somatic mutations were not identified in the single family with the germline ERBB2 mutation and NSCLC and inconsistently in individuals and families with EGFR/ERBB1 mutations." (PMID 34274969, 2021).
tumor (continued). "Consequently, the EGFR-independent kinase function could give tumor cells enhanced survival and growth capacity by contributing to metabolism deregulation, even in the presence of chemotherapeutic agents and TKIs." (PMID 34445451, 2021). "The presence of these AXL-positive cells was not restricted to tumor-derived cell lines harboring EGFR-oncogenic mutations, as we observed that a similar percentage of AXL-positive cells were present also in cell lines driven for example by mutant KRAS (i.e., A549)." (PMID 34254585, 2021). "EGFR overexpression might contribute to deregulated cellular processes, such as uncontrolled proliferation, invasion, DNA synthesis, angiogenesis, cell motility and inhibition of apoptosis, which makes it a molecular target for tumor therapy." (PMID 34237060, 2021). "Lu and colleagues corroborated the evidence, demonstrating that E-cadherin internalization undergoes caveolin-mediated endocytosis in response to epithelial growth factor (EGF) in a human tumor cell line overexpressing EGF receptor (EGFR), a mechanism which may be relevant to the EMT in cancers." (PMID 34948155, 2021). "While these methods disclose high specificity, sensitivity remains relatively low with false negatives being reported, as circulating tumor DNA may not express EGFR mutations in all patients whose tumors harbor mutations." (PMID 33925308, 2021). "Finally, we report that Neuron Navigator-3 (NAV3), a known tumor suppressor downstream of EGFR, is mutated exclusively in non-responders." (PMID 34298611, 2021). "In NSCLC patients with high PD-L1 expression (>50%), EGFR-TKI targeted therapy-induced an increased expression of CD73 in tumor cells compared to baseline and might explain, in part, the poor efficacy obtained in some patients in response to ICI targeting programmed death 1 (PD1) on T cells." (PMID 33430239, 2021). "This indicates that miR-34a may act as a tumor suppressor by targeting EGFR." (PMID 34696703, 2021). "In addition to driving tumor progression, EGFR activation is closely related to PD-L1 signaling." (PMID 34065396, 2021). "Notably, intrapatient concordance was also found for the clinically relevant target genes ERBB2 and EGFR, including in comparison with the primary tumor of one patient with ERBB2 amplification (9 additional copies in the primary and 17 and 18 additional copies in the two metastases)." (PMID 33325154, 2021). "The exogenous upregulation of both can inhibit the tumor formation capacity of HUVECs, increasing the proliferation activity and migration rate, as well as inducing G0/G1 arrest, along with the suppression of epidermal growth factor receptor (EGFR), p38 and cyclin D1." (PMID 33869059, 2021). "Moreover, exosomes surface membrane proteins like CD317, CD91 and EGFR might represent potential tumor makers." (PMID 36046776, 2020). "Overall our findings suggest that while EGFR mutation status does not affect overall recurrence or survival, metastatic vs local recurrence may be influenced by tumor molecular genetics." (PMID 32523650, 2020). "In summary, these data suggest that prolonged treatment with palbociclib induces tumour re-wiring leading to increased expression of growth factor signalling which provides an alternate mitogenic cue in RB competent models which is sensitive to EGFR/ERBB inhibition." (PMID 32307447, 2020). "Interestingly, EGFR expression also strongly correlated with the residual tumor size, suggesting that activation of RasGEFs might directly or indirectly define the growth of a subset of TNBC tumors after chemotherapy." (PMID 32298357, 2020). "Using FDG tumor uptake as a predictor of EGFR status could be worth exploring." (PMID 32742498, 2020). "However, the primary tumor did not contain EGFR exon 18 and 20 mutations but an activating EGFR exon 19 mutation (p.P753Q) which was observed in neither the CSF liquid biopsy nor in the bone metastasis." (PMID 31903155, 2020).
tumor (continued). "Consequently, the question arises as to whether co-occurring genetic alterations cooperate with the primary driver EGFR gene in promoting tumor progression and limiting efficacy of target therapy." (PMID 33520716, 2020). "Complete tumor elimination could be achieved via intratumoral application in three different tumor mouse models (glioblastoma, breast cancer, adenocarcinoma), and in a disseminated EGFR overexpressing tumor mouse model." (PMID 32917034, 2020). "EGFR inhibition could increase radiosensitivity of various tumours." (PMID 32963499, 2020). "Thus, it is tempting to speculate that at least one of the roles of PP2A‐B56 as a tumor suppressor can be explained by its ability to restrict ADAM17‐mediated EGFR signaling." (PMID 32400009, 2020). "Over-activation of the mitogenic EGFR signaling pathway can establish a tumor model in the fly midgut, therefore, a constitutively active form of Ras oncogene at 85D (also known as RasV12) was induced by esgts>Gal4 to activate EGFR signaling pathway in the progenitor cells." (PMID 33057338, 2020). "It was later determined that RhoB elicits this tumor suppressive function in cell lines by inhibiting basal phosphorylated Akt levels of all three isoforms (Akt1, 2 and 3) through modulation of the level of epidermal growth factor receptor (EGFR) on the cell surface." (PMID 32992837, 2020). "Also, recent meta-analyses demonstrated that patients with a BRAF V600E–mutated tumor do not benefit from the addition of anti-EGFR mAbs." (PMID 31705176, 2020). "However, impacts of TAM polarization on ligand production are complex, and tumor EGFR signaling may likewise influence TAM polarization." (PMID 32665556, 2020). "We propose an end-to-end BigBiGAN-based DL approach to predicting the efficacy of EGFR-TKI therapy in patients presenting with stage IV EGFR variant–positive NSCLC without requiring manual tumor volume delineation or feature engineering procedures of traditional radiomics." (PMID 33331920, 2020). "Patients with RAS mutant-type or right-sided mCRC cannot benefit from cetuximab, and only the patients with both RAS wild-type and left-sided mCRC are candidates for anti-EGFR therapy, while bevacizumab shows efficacy regardless of the tumor location or RAS mutation status." (PMID 32704062, 2020). "We hypothesize that the strong negative correlation could be due to different “strategical focuses” of the tumor cells with strong expression of EGFR in areas of cell proliferation and the strong expression of GFAP in areas of tumor invasion, as proposed before." (PMID 33066251, 2020). "Patients who respond to EGFR-TKIs initially experience good clinical therapeutic effects, though, inevitably, after 11–13 months of treatment, some new resistance mechanisms develop as the tumor cells adapt to the treatment, which is termed “acquired resistance”." (PMID 32549388, 2020). "Thus, the detection of tumor mutations through the BL, contribute to the monitoring of the disease and determine the response to treatment as is the case of anti-EGFR therapy in which only patients with the KRAS gene without mutations respond." (PMID 32629823, 2020). "Hence, our study revealed a significant correlation between a high risk score and immunosuppression and its association with the growth and differentiation of B and T cells, and high expression of PLAU, APP and EGFR were the main factors of tumor immunosuppression." (PMID 33232279, 2020). "An anti-EGFR scFv was fused to the plant toxin gelonin (rGel) to get a targeted toxin, which could selectively bind EGFR-overexpressing cells with high affinity and significantly suppressed the tumor growth of human NSCLC." (PMID 33392074, 2020).
tumor (continued). "However, despite the intersection of signalling activation in different tumours, there may be a preference for EGFR‐activated signalling transduction for the metastasis of tumour cells." (PMID 33304472, 2020). "According to the analysis results, we hypothesized that tumor ancestors harboring EGFR mutations would undergo negative selective pressure from B cell infiltration during the acquisition of invasiveness." (PMID 33247113, 2020). "Besides, in both tumor tissue and plasma samples, EGFR mutations occurred with a higher rate in non-smokers and female patients compared to the remaining groups (P < 0.001)." (PMID 32746896, 2020). "Interestingly, we observed that USP25 mRNA levels are significantly higher in patients with stronger EGFR expression compared with patients with lower EGFR levels in all the tested tumor types, reinforcing the concept of a functional connection between EGFR and USP25." (PMID 33202887, 2020). "However, in the past decade, numerous studies identified that tumour cells could harness extracellular vesicles (EVs) to disseminate EGFR, mutant EGFR, phosphorylated EGFR and EGFR ligands to local and distant cells." (PMID 33143170, 2020). "These pathways may be required for neoplasia in this EGFR driven tumor model." (PMID 32737065, 2020). "Interestingly, the EGFR tyrosine kinase receptor, overexpressed in many different tumors and well known for its oncogenic functions in tumor cells, has been recently proposed as a key regulator also of immune cells, as it has been found able to inhibit CTLs through different mechanisms." (PMID 32024070, 2020). "However, in xenograft tumor tissues, we found that genistein treatment strikingly reduced EGFR levels (P<0.05), suggesting that long-term genistein treatment may inhibit EGFR expression." (PMID 32276266, 2020). "Tepotinib along with the EGFR inhibitor osimertinib are be tested in combination to determine whether these two drugs have synergistic anti-tumor activity on MET-positive NSCLCs and the study is estimated to be completed in 2023 (Clinicaltrials.gov identifier: NCT03940703)." (PMID 33182254, 2020). "EGFR inhibitors may limit tumor repopular through the cytostatic effect." (PMID 32963532, 2020). "Merlin, the neurofibromatosis type 2 (Nf2) tumor suppressor, inhibits activation of EGFR and suppresses the internalization of EGFR by NHE-RH1-mediated Merlin-EGFR association, which subsequently leads to the proliferation of CC cells by preventing the formation of EGFR complexes with its targets." (PMID 32708604, 2020). "Western blot analysis demonstrated that while the evaluated EGFR-mutated NSCLC cell lines expressed various levels of IGF-1R protein, AXL-low-expressing tumor cells reported higher levels of phosphorylated IGF-1R (pIGF-1R) compared to AXL-high tumor cell lines." (PMID 32929081, 2020). "Resistance could be explained by genetic alterations in other ancillary axes signaling pathways governing tumor growth, in addition to the tyrosine kinase receptor EGFR, representing a cross-RTK signaling switching that cannot be captured by targeting single RTK." (PMID 33213472, 2020). "Therefore, we speculated that EGFR signalling is possibly involved in tumour cell survival under the pharmacological pressure of BET inhibition." (PMID 31937753, 2020). "Thus, in the current study, the expression of EGFR protein was assessed in the dissemination cascade—throughout the disease process from primary tumours to disseminated circulating tumour cells (CTCs) and metastatic samples obtained from castrate-resistant PCa (CRPC) patients at the time of death." (PMID 32901137, 2020). "In this study, target expression (in this case EGFR) and the amount of shedded receptor (e.g., sEGFR), tumor size, location, drug (e.g., cetuximab) PK, perfusion, and metabolic activity were evaluated as factors that could affect [89Zr]Zr-cetuximab tumor accumulation." (PMID 31705176, 2020).
tumor (continued). "However, the effects of EGFR inhibition on tumours is often short lived." (PMID 32054454, 2020). "While osimertinib inhibited the viability of all EGFR-mutated NSCLC cell lines tested in a dose-dependent manner, the IC50 (half-maximum inhibitory concentration) values were lower in AXL-low-expressing tumor cell lines compared to the AXL-high-expressing tumor cell lines." (PMID 32929081, 2020). "Another technique to develop novel anti-EGFR agents is to enclose conventional EGFR blockers within other agents such as nanoparticles, liposomes, and other protein-based drug delivery systems, which have shown promising tumor affinity and drug efficacy in several preclinical studies." (PMID 32296018, 2020). "We find in PDX models that 4D MLD is consistently somewhat better than 3D MLD, which may relate to the notion that not all EGFR alleles in the tumour may have acquired resistance mutations to the EGFR inhibitor therapy." (PMID 32572029, 2020). "Moreover, poly(N-(2-hydroxypropyl)methacrylamide)-based copolymers labeled with fluorescent dyes were targeted with the EGFR-binding oligopeptide GE-11 (YHWYGYTPQNVI), human EGF or anti-EGFR monoclonal antibody cetuximab were all able to actively target the surface of EGFR-positive tumor cells." (PMID 31906300, 2020). "Therefore, a liquid biopsy using cell-free circulating tumor DNA was performed for assessment of EGFR mutation status, because there were no metastatic lesions accessible for rebiopsy." (PMID 33267781, 2020). "Beyond that, lack of specificity is assumed for diverse TKIs including erlotinib and gefitinib, suggesting putative further targets of strong homology such as ERBB2/HER2 which might be especially noticeable in the pool of p-SCC cells derived from a tumor with heterogeneous EGFR expression." (PMID 32978523, 2020). "The size-dependent and shape-dependent optical properties of the GNPs covalently attached to EGFR antibodies changed the optical properties of the cancerous cells into which they were absorbed, which makes the cells easily identifiable on hyperspectral imaging, even in apparently tumor-free tissue." (PMID 31963462, 2020). "Additionally, increasing evidence has demonstrated that EGFR-mutant NSCLC is not a single-oncogene disease, and both EGFR-mutated and wild-type cancer cells can exist in the same tumor." (PMID 32067121, 2020). "The ICD is known to be supported by tumor destruction, either by necrosis, apoptosis, or mixed death pathways in response to chemotherapy (e.g., doxorubicin, oxiplatin); radiotherapy; epidermal growth factor receptor (EGFR) targeting cetuximab immunotherapy; or immune checkpoint inhibition therapy." (PMID 32872532, 2020). "However, the positive sorting method based on CTCs surface markers (EpCAM, EGFR and other surface markers) cannot obtain more representative tumor cells, resulting in missed selection of many cells with different molecular phenotypes, which has severely restricted the CTCs application value." (PMID 33208163, 2020). "Most notably, in cases in which tumour tissues could not be analysed, additional mutations affecting the actionable genes EGFR and ROS1 were detected in BW samples." (PMID 32441866, 2020). "Although tumor PD-L1 expression could not be assessed in our control EGFR-mutated group due to a lack of available tumor samples, these information suggest that sPD-1 and sPD-L1 may play a part in resistance to anti-PD1 therapies in this specific population." (PMID 32085544, 2020). "Furthermore, tumor tissue with NT5DC2 overexpression collected from subcutaneous xenograft tumor models had significantly higher EGFR expression, while tumor tissue with NT5DC2 knockdown had significantly lower EGFR expression compared with that of their vector controls." (PMID 32382041, 2020).